TRBJ2-2 (T cell receptor beta joining 2-2)
Description:
J region of the variable domain of T cell receptor (TR) beta chain that participates in the antigen recognition. Alpha-beta T cell receptors are antigen specific receptors which are essential to the immune response and are present on the cell surface of T lymphocytes. Recognize peptide-major histocompatibility (MH) (pMH) complexes that are displayed by antigen presenting cells (APC), a prerequisite for efficient T cell adaptive immunity against pathogens. Binding of alpha-beta TR to pMH complex initiates TR-CD3 clustering on the cell surface and intracellular activation of LCK that phosphorylates the ITAM motifs of CD3G, CD3D, CD3E and CD247 enabling the recruitment of ZAP70. In turn ZAP70 phosphorylates LAT, which recruits numerous signaling molecules to form the LAT signalosome. The LAT signalosome propagates signal branching to three major signaling pathways, the calcium, the mitogen-activated protein kinase (MAPK) kinase and the nuclear factor NF-kappa-B (NF-kB) pathways, leading to the mobilization of transcription factors that are critical for gene expression and essential for T cell growth and differentiation. The T cell repertoire is generated in the thymus, by V-(D)-J rearrangement. This repertoire is then shaped by intrathymic selection events to generate a peripheral T cell pool of self-MH restricted, non-autoaggressive T cells. Post-thymic interaction of alpha-beta TR with the pMH complexes shapes TR structural and functional avidity.
Synonyms: TRBJ22; TCRBJ2S2
Gene: T-cell receptor joining (J) gene on chromosome 7 (142,796,560 to 142,796,610, forward strand). Ensembl gene ENSG00000211765.
Subcellular location: Cell membrane
Diseases named in the same sentence as TRBJ2-2 in open-access papers:
TRBJ2-2 is named in the same sentence as 2 diseases in open-access papers, as found by Europe PMC text mining. Sharing a sentence is not in itself a finding about the gene and the disease. The quoted sentences say what the papers report.
Sjögren's syndrome (1 paper, 2025). "For the β chain, many V/J genes, which were highly expressed in cachexic HCC mice, were associated with type I diabetes, such as Trbv1 [S18,19], Trbv13‐2 [S19], Trbj2‐7 [S19,20] and with Sjögren's syndrome, such as Trbv3 [S21], Trbv16 [S22] and Trbj2‐2 [S22]." (PMID 40665793, 2025).
TRBJ2-2 also shares sentences with these, for which no sentence is quoted: type I diabetes (1 paper).